MTOR (mechanistic target of rapamycin kinase)
Diseases named in the same sentence as MTOR in open-access papers (continued):
Sharing a sentence is not in itself a finding about the gene and the disease.
infection (continued). "To determine if induction of canonical autophagy would either increase bacterial clearance or generate additional nutrients that support bacterial replication, we artificially induced autophagy throughout infection with the mTOR inhibitor Torin1." (PMID 23966861, 2013). "Here, we report that infection of macrophages with F. tularensis triggers the phosphorylation of mTOR downstream effector molecules, and that signaling via TLR2 is necessary for these events." (PMID 24312679, 2013). "If patients with LVAD and specific risks such as infection receive Thymoglobulin induction plus early mTOR inhibition, the intensity of immunosuppression accumulates to an intolerable level with an associated increase in infection-related mortality." (PMID 24382994, 2013). "The ratio of phospho- S6 ribosomal protein to unphosporylated S6 ribosomal protein decreased progressively over the course of infection, which is consistent with mTOR inhibition and thus autophagy induction." (PMID 23966861, 2013). "The data suggest that sequestration of mTOR and its activator Rheb-GTP in the AC helps maintain mTOR activity and protect mTOR from inhibition by cellular stress responses induced during lytic infection." (PMID 23028305, 2012). "Two days after infection, western blot analyses confirmed an 85–96% knockdown in mTOR protein level that remained stable for 5 days." (PMID 22110663, 2011). "Elle est favorisée par les reprises chirurgicales, le diabète, l’obésité, le rejet, l’infection pariétale et enfin par les corticoïdes et les inhibiteurs du mTOR." (PMID 22087350, 2010). "gondii infections have opposing effects on host Akt/mTOR signaling for their own benefit, which may present new therapeutic targets." (PMID 42193903, 2026). "Research has shown that the dynamic balance of the PI3K/Akt-mTOR pathway is one of the key factors determining the outcome of infection: the host enhances immune defense by activating this pathway, while pathogens achieve immune evasion by targeting key molecules in the pathway." (PMID 41982459, 2026). "We hypothesize that infection-driven perturbations of mTOR form a mechanistic axis linking peripheral immune dysregulation, BBB compromise, and neural circuit dysfunction." (PMID 41462744, 2025). "We next tested the effects of PA infection on mTOR signaling using HCECs." (PMID 39791872, 2025). "This pathogen-specific vulnerability suggests that Bb’s infection strategy either critically depends on host mTOR activity or exhibits a reduced capacity to evade or compensate for mTOR suppression, potentially reflecting distinct host–pathogen interactions or fungal evasion mechanisms." (PMID 41148875, 2025). "For example, in young infants the expression of the metabolic regulator mechanistic target of rapamycin (mTOR)—which supports a shift toward anaerobic metabolism during infection—is reduced compared with adults, contributing to a more tolerogenic functional profile." (PMID 41157621, 2025). "Based on the current results, we are unable to infer any clear regulatory effect that the Ras-PI3K-Akt-mTOR signaling pathway might have on de novo nucleotide metabolism during WSSV infection." (PMID 40264189, 2025). "Another consideration for measuring mTOR in circulation is whether it fluctuates acutely with an infection due to immune cell proliferation." (PMID 40574888, 2025). "In addition, p-PI3K, p-Akt, and p-mTOR protein levels were also declined in the infection group compared to the control group (p < 0.01), while levamisole or 50–100 mg/kg baicalin alleviated the decrease in the protein levels of p-PI3Kand p-Akt (p < 0.05)." (PMID 40427533, 2025). "The mechanisms of mammalian target of rapamycin (mTOR) signaling as a promotor of glycolysis and a regulator of inflammatory cytokine production are discussed across various immune cell types during infection." (PMID 41511331, 2025).
infection (continued). "Immunoblotting revealed that mTOR and p-mTORS2448 levels were significantly reduced upon EV-D68 infection, suggesting that EV-D68 impairs mTOR signaling, which may contribute to increased LARP1 binding to viral RNA while potentially affecting LARP1 activation." (PMID 40294010, 2025). "Immunosuppressive regimens influence the immune response, and mTOR inhibitors may protect against breakthrough infection." (PMID 40573897, 2025). "mTOR is also a regulator of immune cells, thereby influencing the control of infection." (PMID 38515037, 2024). "Moreover, our findings concur with previous studies, suggesting that mycobacteria can concurrently activate both the mTOR and autophagy pathways, implying an mTOR-independent canonical autophagy activation during such infections." (PMID 38912807, 2024). "We speculate that the mTOR/eIF4E pathway could be activated to different extents after the infection of EB virus, and thus boost the generation of abnormal peptides." (PMID 38994917, 2024). "Our findings revealed a uniform trend in PDCD4 expression levels in TOSI cells infected with these strains at both 3 and 24 hours post-infection, highlighting the widespread and pronounced activation of mTOR activity and subsequent PDCD4 degradation in various mycobacterial infections." (PMID 38912807, 2024). "The present study demonstrates the differences in the activation of mTOR signaling by the avirulent (Iowa) and highly virulent (SS) strains of R. rickettsii during the infection of cultured human ECs mediated by both C1 (Raptor-mediated) and C2 (Rictor-based) mTOR complexes." (PMID 38399700, 2024). "In addition, these pathogenic bacteria can subvert host metabolism by targeting mTOR complexes for their replication and the establishment of infection." (PMID 38399700, 2024). "mTOR inhibitors rapamycin and Torin2 significantly increased bacterial growth and replication in the ECs, as evidenced by a more than six-fold increase in rickettsia copy numbers at 48 h post-infection." (PMID 38399700, 2024). "Therefore, compared to the CG group, regulating the key gene rictor in the mTOR pathway by down-regulating miRNA expression is an important immune process in T. rubripes against infection." (PMID 39452097, 2024). "Our findings show that rickettsiae likely exploit mTOR during infection to interfere with the autophagic response and promote replication in host ECs, as our data suggest that the inhibition of mTOR with low doses of rapamycin and Torin2 promotes rickettsial replication." (PMID 38399700, 2024). "IRF1 could inhibit the mechanistic target of rapamycin (mTOR)/p70 S6 kinase (p70 S6K) cascade to suppress Mtb-infection in macrophages." (PMID 38625657, 2024). "Mechanistically, the infection of ASFV triggers the AKT/mTOR/NF-κB signaling pathway." (PMID 39000284, 2024). "One explanation may be apotential override of mTOR/NF-κB crosstalk during infection with abona fide pathogen in the context of a complex invivo host immune response." (PMID 38767353, 2024). "The identified mechanism, involving IFN-γ-induced suppression of CD115-dependent mTOR signaling in macrophages, provides insights into the adaptation of macrophage subsets during infection and highlights a crucial aspect of host defense against intracellular pathogens." (PMID 38377133, 2024). "In addition, S. Typhimurium prevented TFEB mitochondrial translocation at later time point of infection, which correlates with our previous findings that it activates mTOR and thereby inhibits autophagy." (PMID 38263327, 2024). "The findings also suggested that the proteins might be activated at various points during infection to control autophagy by regulating the mTOR pathway." (PMID 39457551, 2024). "Interestingly, the high dose OA+EO treated group showed a similar profile to the infection group, with a limited number of phosphorylation changes but among those pro-inflammatory and proliferative (for example NFkB, mTOR, IRS1, HSP90)." (PMID 38835764, 2024).
infection (continued). "To investigate whether the transcriptional activity of CEBPB on DEFB1 is regulated by the AMPK and mTOR pathways and the resulting truncation of CEBPB, we first examined the activation of AMPK and mTOR in AEC-II cells after H37Rv infection." (PMID 38397085, 2024). "The relation between Feline Herpesvirus type 1 (FeHV-1), a primary pathogen in cats, and PI3K/Akt/mTOR pathway (as well as the changes that its infection causes in the processes activated by this pathway), has not yet been investigated." (PMID 37026095, 2023). "According to what is present in the literature, it would seem that FeHV-1 uses the PI3K/Akt/mTOR axis mainly for its entry (already 30 min post infection), then induces autophagy (at 12 h post infection), mitochondrial damage (at 24 h), and complete apoptosis (at 48 h)." (PMID 38087282, 2023). "Furthermore, treating NHDFs with the mTOR inhibitor, PP24254 demonstrated that mTOR was required for the increase in both intracellular and extracellular lactate that is produced in response to infection with iF17." (PMID 38036506, 2023). "mTOR expression in the mitochondrial autophagy inducer group was 1.360 ± 0.479, which was comparable to that in the control group and infection model group (P > 0.05) but was significantly higher than that in the AKT2 inhibitor group and mitochondrial autophagy inhibitor group (P < 0.05)." (PMID 37077346, 2023). "(d) Heat map of m6A peaks related to mTOR pathway in T47D cells infected with retrovirus encoding sgMETTL3 resistant METTL3-WT, METTL3-Δ198, METTL3-Δ238, or control vector (Vec) followed by another infection with sgMETTL3 or sgControl (sgCtrl)." (PMID 37589705, 2023). "The capacity of the ZIKV to cross the CTB barrier seems to be the result of a sum of factors, including greater infection and replication efficiency, better capacity to activate the mTOR machinery, and a limited inflammatory and chemotactic response with low IFN activity." (PMID 37227282, 2023). "Moreover, AKT/mTOR is inhibited by ursolic acid to promote autophagy and suppress the necroptosis of macrophages, enhancing the anti-infection effect against Mycobacterium tuberculosis." (PMID 38164133, 2023). "Moreover, tetramethylrhodamine ethyl ester (TMRE) staining showed that infection increased mitochondrial membrane potential in an mTOR-dependent manner (Murphy, 2009)." (PMID 36103894, 2022). "Moreover, The HA protein bound with HSP90AA1 to inhibit the AKT/mTOR signalling pathway and inducing complete autophagy to degrade innate immunity factors in early infection." (PMID 34967267, 2022). "Inhibition of the PI3K-Akt-mTOR signaling pathway can affect post-infection inflammatory, apoptotic, and autophagic responses, protecting host cells from various pathogens, including Mycobacterium tuberculosis, Legionella pneumophila, and Listeria monocytogenes." (PMID 35958147, 2022). "Together, these findings suggest that baseline mTOR-facilitated mitochondrial metabolism is insufficient to protect macrophages from mycobacterium-induced death; adaptive infection-induced mTOR activity and corresponding increases in mitochondrial metabolism are required." (PMID 36103894, 2022). "Likewise, the inhibition of SIRT1 related to suppressed mTOR activation and resulted in reduced inflammation and damage in the lung after infection." (PMID 34952202, 2022). "By transcription factor analysis, we detected that EZH2 is the key regulator of the NKT subset in CRKP infection conditions, which could mediate mTOR pathway activation." (PMID 36556247, 2022). "In the present study, M. bovis activated the early autophagic response in bMECs and inhibited autophagy by activating the PI3K-Akt-mTOR signaling pathway at later stages of infection, whereas downregulation of PTEN gene expression promoted replication of M. bovis in bMECs." (PMID 35958147, 2022).
infection (continued). "Poor elimination of the bacteria despite the high levels of autophagy induced during infection leads us to hypothesize that the activation of the mTOR pathway interferes with the bacteria elimination." (PMID 36104771, 2022). "Therefore, amplified phosphorylation of proteins in the Akt/mTOR/p70S6K pathway revealed a host response that negatively regulated this signaling cascade after infection by a virulent H5N1 virus." (PMID 36059479, 2022). "In addition, mTOR limits the production of pro-inflammatory cytokines and promotes anti-inflammatory cytokines during infection." (PMID 36061862, 2022). "In addition, the mTOR blockade at the time of injury increases the ability of mice to clear infection late after injury." (PMID 35955914, 2022). "No significant changes in the phosphorylation of S6 were observed, suggesting that autophagy inhibition by BCG pre-infection is not caused by regulation of the mTOR pathway." (PMID 36104771, 2022). "Thus, mTOR inhibitors can be continued in a clinical setting for mild infections; however, they should be discontinued if the severity of the infection increases." (PMID 35246210, 2022). "To validate the upregulation of mTOR-related modules in the endothelial cells of BPD we compared the modules differentially expressed in BPD to the modules from endothelial cells from an infection mouse model." (PMID 35508467, 2022). "It is well accepted that the mTOR axis regulates inflammation and innate immune cell function; however, no study has established a mechanistic link between the immune dysfunction, subsequent infection control, and the mTOR axis after B+I injury." (PMID 35955914, 2022). "Resolution requires cessation of the mTOR agent and treatment of infection." (PMID 36354934, 2022). "The RAP1, mTOR, and platelet activation pathways were activated during the infection period." (PMID 36569953, 2022). "Thus, mTOR exerts its cytoprotective effect by supporting glycolysis both in Mm zebrafish infection and Mm- and Mtb-infected human macrophages." (PMID 36103894, 2022). "Notably, this increase only reached baseline WT levels, tracking with infection-induced increases in mitochondrial metabolism (mROS and TMRE) to baseline WT levels in mTOR-deficient conditions." (PMID 36103894, 2022). "TRIM22 was knocked down and overexpressed in HUVECs followed by infection with DENV-2 to further explore whether TRIM22 mediates DENV-2-induced autophagy through the AMPK/ERK/mTOR pathway." (PMID 36587218, 2022). "mmpL7 mutant Mm infection did not kill mTOR-deficient macrophages, as evidenced by the lack of cording in the animals." (PMID 36103894, 2022). "During infection with mycolactone-competent Mul, we observed a significant activation of mTOR." (PMID 35401531, 2022). "This suggests that perhaps exosomal miR-99 expression could directly influence mTOR activity in monocytes during infection." (PMID 36061862, 2022). "At this early stage, however, infection did not alter glucose levels and glycolytic capacity, nor did it alter metabolite abundance in either WT or mTOR-deficient cells." (PMID 36103894, 2022). "These properties might play protective roles in blocking SARS-CoV-2 replication and infection at least in part by enhancing endolysosome acidification, increasing autophagy, and inhibiting mTOR-signaling pathways." (PMID 33768214, 2021). "These modes of mTOR inhibition may explain the differences observed in immortalized cells during JCPyV infection; however, it does substantiate the importance of mTOR during infection of primary astrocytes." (PMID 34831441, 2021). "By restricting IV-induced PI3K/mTOR pathway activation, thereby also reversing infection-mediated metabolic changes, the inhibitor BEZ235 was even efficient against IAV in an in vivo mouse model and led to reduced viral titers in their lungs, as well as improved survival rates of the animals." (PMID 34696497, 2021).
infection (continued). "The last decade has witnessed much progress in our knowledge of the properties of lactic acid bacteria (LAB) as probiotic candidates, which include their modulatory functions on specific targets of the PI3K/Akt/mTOR signaling pathway, and their promising effects on infection control." (PMID 33615993, 2021). "Given the recent observations that SARS‐CoV‐2 infection restricts autophagy, it is tempting to speculate that SARS‐CoV‐2, SARS‐CoV and MERS‐CoV share a similar mTOR‐dependent mechanism of infection." (PMID 33190346, 2021). "Autophagy can be induced by pathogen infection and is triggered by the inhibition of mammalian target of rapamycin (mTOR) and Beclin1-phosphatidylinositol-3 kinase (PI3K) complex activation, followed by the initial formation of double-membraned vesicles known as the isolation membrane or phagophore." (PMID 33461581, 2021). "Likewise, we found that treatment with chrysin increased the phosphorylation of mTOR in A/PR/8-infected cells, which was otherwise decreased by A/PR/8 infection, suggesting that chrysin inhibited autophagy through the regulation of mTOR." (PMID 34372556, 2021). "Together, these data highlight that SARS-CoV-2-infected cells have decreased mTOR expression and perturbation in autophagy and mitochondrial processes, which, in turn, could properly impede the immune response to infection." (PMID 33796130, 2021). "Conditioning regimens (including chemotherapy and/or radiation) prior to transplantation, agents given for prevention of acute GVHD such as calcineurin or mammalian target of rapamycin (mTOR) inhibitors, infection, and the graft-versus-host reaction itself can all contribute to endothelial injury." (PMID 34924021, 2021). "The ratio of total mTOR and p-mTOR showed reduced activation of mTOR during infection (p < 0.01)." (PMID 34513730, 2021). "Moreover, the use of the mTOR inhibitor Ku-0063794 or the mTORC1 inhibitor rapamycin did not affect the ability of IRF3 to accumulate into the nuclear compartment following the infection of primary fibroblasts with SeV." (PMID 33411856, 2021). "Our results reveal a previously unknown role of the IL-1β/MyD88/mTOR axis in modulating mucosal Tregs during an infection." (PMID 33240286, 2020). "AM from infected animals showed down-regulation of the mTOR pathway, unfolded protein response, and phagocytosis function together with the reduction of metabolic pathways related to their altered energetic capacity upon infection." (PMID 33365028, 2020). "Importantly, detection of p4EBP1 in Ag-expCD4+ T cells on days 5 and 15 of infection was almost completely blocked (similar to background staining within naive T cells) by treatment with the pan mTOR inhibitor Torin." (PMID 32817333, 2020). "Together, these data highlight that SARS-CoV-2 infected cells have decreased mTOR, perturbation in autophagy and mitochondrial processes, which in turn could impede proper the immune response to infection." (PMID 32511341, 2020). "mTOR signaling also impacts immunity in aging: inhibition of mTOR signaling improves hematopoiesis in aged mice as well as immune function in the contexts of vaccination and infection in elderly humans." (PMID 33170123, 2020). "Moreover, it has been shown to regulate the inflammatory activity of monocytes in response to infection in an mTOR‐dependent manner." (PMID 32567735, 2020). "To determine further whether induction of the autophagy cascade is governed by mTOR, we transfected ECs with either mTOR-specific or a control siRNA for 48 h prior to infection of cells with R. rickettsii and analysis of LC3-II lipidation." (PMID 33003310, 2020). "Again, the levels of total mTOR remain relatively unchanged through the course of infection." (PMID 33003310, 2020).